AQP3 (aquaporin 3 (Gill blood group))
Diseases named in the same sentence as AQP3 in open-access papers (continued):
Sharing a sentence is not in itself a finding about the gene and the disease.
breast carcinoma (continued). "AQP3 plays a critical role in the migration of human breast cancer cells induced by fibroblast growth factor-2 (FGF-2)." (PMID 30555637, 2018). "Studies have shown that an ERE in the AQP3 gene mediates estrogen-induced cell migration and invasion in estrogen receptor-positive breast cancer cells." (PMID 30285121, 2018). "AQP3 has proven to serve as a potential prognostic marker after curative surgery in early breast cancer demonstrating human epidermal growth factor receptor 2 (HER2/neu, c-erbB2) overexpression." (PMID 30555637, 2018). "In breast cancer, increased AQP3 expression affects cell migration and invasion by regulating the expression of EMT-related factors and influencing the reorganization of the actin cytoskeleton." (PMID 30285121, 2018). "AQP3 has been shown to control breast cancer cell migration via regulation of hydrogen peroxide (H2O2) transport, influencing downstream signaling." (PMID 30555637, 2018). "This was associated with higher histological grade and increased spreading to lymph nodes highlighting the importance of AQP3 in breast cancer progression." (PMID 28991174, 2017). "In breast cancer cells expressing estrogen receptor, stimulation with estrogen transcriptionally upregulated the levels of AQP3." (PMID 28991174, 2017). "In cell cultures, AQP3 expression was associated with increased migration and invasion of T47D, MDA-MB-231, and DU4475 breast cancer cells, while knockdown of AQP3 significantly reduced migration compared to control cells." (PMID 28991174, 2017). "AQP3 expression in breast cancer cells was increased by the stimulation with 5′-deoxy-5-fluoropyrimidine nucleosides (5′-DFUR), which was used in the chemotherapy of solid tumors." (PMID 25886458, 2015). "This study demonstrated that AQP3 played an important role in E2-induced migration and invasion of ER-positive (T47D) breast cancer cells." (PMID 26219409, 2015). "AQP3 was found as a critical and necessary factor for the migration of human breast cancer cells induced by fibroblast growth factor-2 (FGF-2)." (PMID 25886458, 2015). "Our data showed that, in breast cancer cells, increased expression of AQP3 would upregulate the expression of Snail, downregulate the expression of E-cadherin, and, influence the formation of filopodia and the rearrangement of stress fibers." (PMID 26219409, 2015). "Knockdown of AQP3 significantly attenuated migration and invasion of breast cancer cells, and over-expression of AQP3 significantly enhanced these two processes." (PMID 26219409, 2015). "We, for the first time, reported that ER-positive breast cancer tissues obtained from premenopausal patients had higher AQP3 expression when compared to those obtained from postmenopausal patients." (PMID 26219409, 2015). "A very recent study has shown that AQP3 is required for FGF-2-induced migration of human breast cancers." (PMID 24338153, 2014). "We will also discuss, below, how AQP1 is thought to be involved in estrogen mediated angiogenesis in the mammary gland and outline how increases in AQP3 expression promote FGF-2 stimulated migration of breast cancer cell lines." (PMID 24338153, 2014). "Several studies have also reported on the expression and functional role of AQP3 in breast cancer cell lines." (PMID 24338153, 2014). "The study concluded that AQP3 is required for FGF-2-induced cell migration in cultured human breast cancer cells." (PMID 24338153, 2014). "In summary, our findings suggest a novel function of AQP3 in cell migration and metastasis of breast cancers." (PMID 23468877, 2013). "Our findings that AQP3 facilitates FGF-2-induced cell migration in breast cancer cells are consistent with the recent reports that AQPs is involved in many physiological and pathological functions, including cell migration." (PMID 23468877, 2013). "It is notable that the FGF-2-induced AQP3 up-regulation coincided with the FGF-2-induced migration in the two representative breast cancer cell lines." (PMID 23468877, 2013).
breast carcinoma (continued). "Potential role of AQP3 was examined using two representative breast cancer cell lines (MDA-MB-231 and Bcap-37)." (PMID 23468877, 2013). "AQP3-related mRNA levels dramatically increased (8-fold) after treatment of MCF7 breast cancer cells with the capecitabine catabolite, 5′-deoxy-5-fluorouridine (5′-DFUR), a direct precursor of 5-fluorouracil (5-FU)." (PMID 23017148, 2012). "Additionally, in estrogen receptor (ER)-positive breast cancer cells, upregulation of AQP3 contributes to cell migration and invasion through the modulation of EMT-related markers and reorganization of the actin cytoskeleton." (PMID 39941100, 2025). "However, Overexpression of AQP3 in T47D breast cancer cells reduced E-cadherin protein levels while increasing Snail expression." (PMID 38336645, 2024). "Estradiol upregulates AQP1 in prostate cancer; AQP2 in EC; and AQP3 in breast cancer." (PMID 37760476, 2023). "Genotyping of seven AQP3 SNPs in early breast cancer patients indicated that AQP3 could be a potential prognostic marker." (PMID 36913438, 2023). "In addition, AQP3 has shown to be a potential target for breast cancer stemness, as demonstrated by a study on the anti-cancer effects of cold atmospheric plasma (CAP)." (PMID 38136293, 2023). "Moreover, it has been demonstrated that estradiol increases AQP3 mRNA and protein expression in cells from human endometrial adenocarcinoma as well as in estrogen receptor (ER)-positive breast cancer cells." (PMID 37190049, 2023). "Breast cancer cell lines provide an interesting model to study relations between AQP3 and the EGFR signaling pathway, as MCF7 are positive for hormone receptors (ER and PR), SkBr3 are positive for human epidermal receptor 2 (HER2), and SUM159PT are negative for both hormone receptors and HER2." (PMID 37175840, 2023). "This work focuses on AQP3 due to its involvement in breast cancer migration." (PMID 37175840, 2023). "Interestingly, an estrogen response element (ERE) in the AQP3 promoter has been identified in estrogen-receptor-positive breast cancer cells." (PMID 37190049, 2023). "This study also found negative associations between the AQP3 gene and protein and breast cancer, indicating the need to elucidate the signaling pathways affected by AQP3." (PMID 37175840, 2023). "AQP3 and AQP9 were associated with worse RFS in breast cancer patients." (PMID 36212456, 2022). "The possibility to use AQP3 as a prognostic marker in breast cancer can be attributed to its role in cell migration, which is facilitated by channelling both, water and glycerol, further resulting in lamellipodia formation and consequently, cell movement and migration." (PMID 33947079, 2021). "Also, SDF-1-induced breast cancer signaling and migration requires aquaporin-3 (AQP3), which is a member of the aquaporin water channel family functioning as water and glycerol transporter." (PMID 34681181, 2021). "Knockdown of AQP3 reduced motility in breast cancer cell lines in response to fibroblast growth factor, suggesting inhibition of AQP3 might control cancer cell migration." (PMID 33499000, 2021). "Since AQP3 was demonstrated to be involved in tumor metastasis and invasion in breast cancer, down-regulation of AQP3 in EBVaGC may explain why EBVaGC has a better prognosis compared with other non-EBV-associated GCs." (PMID 33718209, 2021). "In ER-positive cells, AQP3 is only present at the cell membrane in higher histopathological grades and stage; while these breast cancer cells have higher AQP3 expression and cell membrane localization, increasing tumor hypoxia also increases their growth rate and invasion." (PMID 33917751, 2021). "Work on the MDA-MB-231 breast cancer cell line has shown that knockdown of AQP3 modestly decreases water permeability (17%), but markedly decreases glycerol permeability (77%), indicating AQP3 might be more permeable to glycerol." (PMID 32331274, 2020).
breast carcinoma (continued). "Meta-analyses confirmed predominantly negative associations between AQP protein and RNA expression levels and patient survival times, most notably for AQP1 in lung, breast and prostate cancers; AQP3 in esophageal, liver and breast cancers; and AQP9 in liver cancer." (PMID 32679804, 2020). "In addition, AQP3 expression was reported to affect breast cancer cell migration during metastasis via binding of the chemokine CXCL12 to its receptor CXCR4." (PMID 31379986, 2019). "Thus, also in breast cancer cells, the Nox2/AQP3 complex is required for H2O2 intracellular transport and for H2O2 to exert its downstream cell-signaling effects." (PMID 30893772, 2019). "Also in this case, a complex between AQP3 and Nox2 was found at the leading edge in polarized breast cancer cells, where a transient H2O2 accumulation occurred during CXCL12-induced chemotaxis." (PMID 30893772, 2019). "However, in siAQP5 cells that still express AQP3, oxidative treatment induced a significant recovery at 24 h (50% wound area), similar to control cells, possibly due to H2O2 diffusion via AQP3, as previously reported for breast cancer cells." (PMID 31277235, 2019). "This is illustrated by the finding that AQP3 is required for C-X-C motif chemokine 12 (CXCL12)-induced breast cancer cell signaling and directional migration through a mechanism in which CLCL12-induces the formation of extracellular H2O2 and subsequent internalization." (PMID 30555637, 2018). "AQP3 knockdown cells consistently showed markedly reduced breast cancer cell metastasis to lungs." (PMID 30555637, 2018). "Since estrogen is critical for development and progression of breast cancer, we investigated whether E2 could enhance AQP3 expression in ER-positive breast cancer cell line (T47D) or ER-negative breast cancer cell line (MDA-MB-231)." (PMID 26219409, 2015). "The results were further verified by Western blotting analysis, suggesting that AQP3 might act as a positive regulator of the EMT signaling pathways during the metastasis of breast cancer, although the mechanisms was yet unknown." (PMID 26219409, 2015). "Here we show that AQP3 is an important enforcer of migration and invasion in breast cancer." (PMID 26219409, 2015). "However, the regulatory mechanisms for AQP3 expression in breast cancer were still poorly understood." (PMID 26219409, 2015). "We, for the first time, identified an ERE in the promoter of AQP3 gene, and found that estrogen might promote breast cancer development through activating ERE in the promoter of AQP3 gene and upregulating AQP3 expression in ER-positive breast cancer." (PMID 26219409, 2015). "We then examined whether estrogen could alter the expression level of AQP3 in breast cancer cell lines." (PMID 26219409, 2015). "To confirm that high AQP3 expression might play an important role in breast cancer progression, we overexpressed AQP3 in T47D cells." (PMID 26219409, 2015). "In the present study, we found that FGFR kinase inhibitor PD173074 significantly inhibited AQP3 expression, as well as cell migration in both MDA-MB-231 and Bcap-37 breast cancer cells, adding support to the putative role of FGFR in cell migration and AQP3 expression in human breast cancers." (PMID 23468877, 2013). "AQP3 is required for FGF-2-induced cell migration in cultured human breast cancer cells." (PMID 23468877, 2013). "To better probe into the mechanisms of this progress, we first investigated whether FGF-2 could induce AQP3 expression in human breast cancer cell lines." (PMID 23468877, 2013). "Similarly to cell volume changes, AQP3 silencing resulted in significant reversion of nucleoside-induced cell growth inhibition in the breast cancer cell line MCF7, and to a lesser extent in the colon cancer cell line HT29 after treatment with 5′-DFUR." (PMID 23017148, 2012). "Thus, it appears that changes in AQP3-related mRNA levels parallel the cytotoxic effects of nucleoside derivatives on breast cancer cells." (PMID 23017148, 2012).
breast carcinoma (continued). "However, it remains unproven if AQP3 may be employed as a breast cancer predictive biomarker or potential target." (PMID 38336645, 2024). "In addition, high expression of AQP3 in triple-negative breast cancer was associated with a worse prognosis, while in HER2-positive breast cancer, AQP3 was in the group of genes predicting worse relapse-free survival after neoadjuvant chemotherapy plus either trastuzumab and/or lapatinib." (PMID 34829727, 2021). "While AQP3 overexpression in early breast cancer patients was shown to be associated with a worse prognosis in patients with the HER2-overexpressing phenotype, AQP1 and AQP5 were reported as independent prognostic markers of survival for breast cancer patients." (PMID 31379986, 2019). "This study aimed to investigate whether AQP3, one of the AQPs expressed highly in breast cancer, had any clinical implication in estrogen-receptor (ER) positive breast cancer, and explore the regulatory mechanisms of AQP3 in estrogen-related breast cancer progression." (PMID 26219409, 2015). "However, whether high expression level of AQP3 in breast cancer has any clinical implication in patients is poorly understood." (PMID 26219409, 2015). "First, we tested whether FGF-2 induces AQP3 up-regulation in human breast cancers." (PMID 23468877, 2013). "However, few reports focused on the potential role of AQP3 in breast cancer." (PMID 23468877, 2013). "However, little is known about the significance of AQP3 in breast cancer." (PMID 23468877, 2013). "Here, we hypothesized that AQP3 in breast cancer could facilitate FGF-2-induced cell migration." (PMID 23468877, 2013). "Recently, AQP1, AQP3 and AQP5 overexpression was reported to disrupt cell polarity in breast cancer by interacting with the protein Scribble, leading to its downregulation." (PMID 39941100, 2025). "The contribution of AQP1, AQP3 and AQP5 to oxidative stress resistance has been investigated in colon and breast cancer cell lines by assessing their expression before and after treatment with H2O2." (PMID 39941100, 2025). "AQP3 was identified as a crucial and required element for the FGF-2-promoted migration of human breast cancer cells." (PMID 38336645, 2024). "Transcriptomic analyses using the Human Protein Atlas database revealed higher mRNA levels of several AQPs in human breast cancer, namely AQP1, AQP3, AQP5, AQP7, AQP9 and AQP11, when compared to overall median AQP expression levels in the biopsies." (PMID 37681917, 2023). "Decreased AQP3-19Y phosphorylation impaired SCAF11-mediated AQP3-5K K48-ubiquitination, resulting in compromised FOXO1 activity in breast cancer stem cell maintenance." (PMID 38136293, 2023). "A previous study performing transcriptomic analyses on breast cancer biopsies revealed increased mRNA expression of AQP1, AQP3, AQP5, AQP7, AQP9 and AQP11 when compared to overall median AQP levels in the biopsies." (PMID 37681917, 2023). "Of note, we recently found that AQP1, AQP3 and AQP5 differentially affected the response of 3D-grown human breast cancer spheroids to conventional anticancer therapies." (PMID 37681917, 2023). "The mRNA expression levels of AQP8, AQP9, and AQP10 were upregulated, while those of AQP3, AQP4, AQP5, and especially AQP7, were downregulated in breast cancer based on the Oncomine database." (PMID 36212456, 2022). "The expression of AQP1, AQP3, and AQP5 has been found to be increased among resected breast cancer samples and carries a prognostic importance." (PMID 35847914, 2022). "AQP3-mediated H2O2 oxidized PTEN and protein tyrosine phosphatase 1B (PTP1B) and activated the Akt pathway in breast cancer cells and lung adenocarcinoma cells." (PMID 35972604, 2022). "Next, we outline the roles in breast cancer of AQP1, AQP3, AQP4, AQP5, and AQP7, which are the only AQPs that have begun to be characterized as having roles in breast cancer progression and as potential prognostic markers." (PMID 36212456, 2022).
breast carcinoma (continued). "AQP1, AQP3, and AQP5 mRNA expression significantly increased in breast cancer tissue compared to normal tissue and localized to the cell membranes by immunohistochemistry." (PMID 36212456, 2022). "AQP3 and AQP5 were detected in human breast cancer tissues, specifically in the membrane and cytoplasm of triple negative breast cancer (TNBC) patients, with AQP5 highly expressed in the invasive front of the tumors." (PMID 36212456, 2022). "Among the 13 human aquaporins, AQP3 and AQP5 were shown to be significantly upregulated in breast cancer indicating their role in the development of this malignancy." (PMID 33947079, 2021). "A few studies have reported the expression of AQPs in breast cancer, mainly AQP1, AQP3, and AQP5, that were found higher expressed in tumors than in normal adjacent tissues." (PMID 31379986, 2019). "AQP3 mediated H2O2 has been described as controlling EGF signaling in epithelial cells and plays an important role in T-cell and breast cancer cell migration." (PMID 30555637, 2018). "Hence, in our view, AQP3 might be a potential target for anti-breast cancer treatment." (PMID 26219409, 2015). "In summary, we conclude that AQP3 is responsible for FGF-2-induced cell migration in human breast cancer cells, and that FGF-2 up-regulates AQP3 expression via the FGFR-PI3K and FGFR-ERK signal transduction pathways." (PMID 23468877, 2013). "A recent study of human breast cancer showed that, among the 13 AQP members, only AQP1, AQP3, and AQP5 expression is elevated in breast cancer tissues relative to normal tissues." (PMID 23468877, 2013). "The results showed that FGF-2 up-regulates AQP3 expression and enhances cell migration in MDA-MB-231 and Bcap-37 breast cancer cells." (PMID 23468877, 2013). "WalBC cells exhibited expression of known markers of basal invasive human breast cancers as well as increased KRT17, KRT 14 and KRT 19, DSP, s100A4, NDRG-1, ANXA1, TK1 and AQP3 gene expression and decreased gene expression of TIMP3, VIM and TAGLN." (PMID 18179684, 2008). "While miRNA-mediated targeting of AQP3 has not been specifically reported in breast cancer, miR-mediated targeting of AQP3 by miR-185-5p, miR-874, and miR-124 has been shown to inhibit cell differentiation in various cancers." (PMID 40244097, 2025). "Enhanced AQP3 channel levels, which mediate H2O2 transport and induce CXCL12-cell signalling and invasion, may enhance breast cancer metastasis." (PMID 38336645, 2024). "Given that numerous studies have shown the role of AQP3 and AQP7 overexpression in promoting breast cancer, the combined inhibition of AQP3 and AQP7 could be a useful strategy in the treatment of breast cancer progression and metastasis." (PMID 39123442, 2024). "AQP1, AQP3, AQP4, AQP5, AQP7, and AQP9 expression were evaluated because these AQPs are expressed in breast tumors and have begun to be characterized as having roles in breast cancer progression and metastasis." (PMID 39123442, 2024). "Here, we investigated whether lipid raft disruption affects AQP3 and its dependence on the EGFR/PI3K/Akt signaling pathway in breast cancer cell lines with different malignant potentials." (PMID 37175840, 2023). "To ensure that this interaction is not the other way around, we silenced AQP3 of breast cancer cells and measured activation of the EGFR/PI3K/Akt pathway." (PMID 37175840, 2023). "In breast cancer, CXCL12/CXCR4-dependent cell migration plays an important role in progression, for which AQP3 is crucial through H2O2 transport via channel activity from AQP3." (PMID 35847914, 2022). "In this review, we discuss the roles of AQP1, AQP3, AQP4, AQP5, and AQP7 in breast cancer progression and metastasis, including the role of AQPs in the tumor microenvironment, to highlight potential contributions of stromal-derived to epithelial-derived AQPs to breast cancer." (PMID 36212456, 2022).